LPL (lipoprotein lipase)
Diseases named in the same sentence as LPL in open-access papers (continued):
Sharing a sentence is not in itself a finding about the gene and the disease.
atherosclerosis (continued). "A growing body of evidence suggests that triacylglycerol lipases, i.e., LPL or EL, may influence the onset and progression of atherosclerosis, i.e., an underlying pathological feature of coronary artery disease." (PMID 37686357, 2023). "Subjects with defective LPL showed an association with the progression of atherosclerosis." (PMID 35456470, 2022). "Artesunate, a derivative of plant-extracted malaria drug artemisinin, was shown to reduce the formation of atherosclerotic plaques, acting through increased expression of KLF2 and LPL (lipoprotein lipase)—the central triglyceride hydrolyzing enzyme, which deficiency leads to atherosclerosis." (PMID 35203463, 2022). "Whether the effect of APOC2-deficiency on atherosclerosis phenocopies the effect of LPL-deficiency in mice needs further investigation." (PMID 32849290, 2020). "Genetic variations in the LPL gene could influence lipid transport and metabolism and could consequently modulate an individual’s susceptibility to atherosclerosis." (PMID 29459423, 2018). "Given the prevalence of the LPL S447X polymorphism in the population, greater knowledge of the underlying consequences of this variation may be of considerable importance in understanding genetic predisposition to atherosclerosis and heart disease." (PMID 16822320, 2006). "LPL is integral to the pathogenesis of atherosclerosis and thrombosis, as evidenced by recent studies." (PMID 40625358, 2025). "LPL has also been discussed as an important factor in atherosclerosis; however, reports are controversial and suggest both pro- and antiatherogenic effects." (PMID 39409049, 2024). "Not only that, but during RC hydrolysis by lipoprotein lipase, the release of FFAs and monoacylglycerol can lead to local inflammation, which is likewise involved in the formation and progression of atherosclerosis." (PMID 38968507, 2024). "Studies assessing agents targeting angiopoietin-like 3 (lipoprotein lipase inhibitor) and apolipoprotein C3 antisense will add further insights into the role of triglycerides in atherosclerosis." (PMID 38667744, 2024). "Specifically, we will focus on LPL function and dysfunction, and its contribution towards the development of both atherosclerosis and cardiomyopathy." (PMID 39081272, 2024). "Lipoprotein lipase plays a crucial role in lipid metabolism, and its dysregulation contributes to developing atherosclerosis and other diseases." (PMID 39044888, 2024). "Nonetheless, new triglyceride-lowering treatments targeting angiopoietin-like 3 (lipoprotein lipase inhibitor) and apolipoprotein C3 antisense will add further insights into the role of triglycerides in the progression of atherosclerosis." (PMID 38667744, 2024). "Lipoprotein lipase (LPL) is a key molecule involved in triglyceride metabolism that plays a significant role in the progression of atherosclerosis." (PMID 36982268, 2023). "Endothelial (EL) and lipoprotein (LPL) lipases are enzymes involved in lipoproteins metabolism and formation of atherosclerosis, a pathological feature of coronary artery disease (CAD)." (PMID 37686357, 2023). "Elucidation of the role of LPL in atherosclerosis was challenging at first because homozygous knockout led to death of Lpl deficient mice soon after birth." (PMID 36994095, 2023). "Plasma levels of ANGPTL8 are known to be higher in atherosclerotic patients, resulting in plasma LPL inhibition and the build-up of circulating lipoproteins, both of which contribute to inflammation and the pathogenesis of atherosclerosis." (PMID 36983346, 2023).
atherosclerosis (continued). "MiR-182 was shown to promote atherosclerosis in animal models by increasing lipid accumulation in atherosclerotic lesions, secretion of proinflammatory cytokines, and activity of lipoprotein lipase." (PMID 35329950, 2022). "The cholesterol transport system is an important component in the regulation of atherosclerosis and the genes associated with itlike APOA1, ABCA1, ABCG1, LCAT, APOB, CETP, LPL, PPARγ, LXR, SR-A, FoxO1, PCSK9,etc." (PMID 35241081, 2022). "From the vast array of genes that are associated with this condition, AGT, LPL, ITGB2, IRS were identified to play vital role in the pathogenesis of atherosclerosis." (PMID 35241081, 2022). "CIH exposure increases serum lipid levels, decreases serum LPL activity, and exacerbates atherosclerosis." (PMID 36285165, 2022). "Lipoprotein lipase (LPL)-mediated triglyceride clearance is important for the suppression of atherosclerosis." (PMID 34579081, 2021). "Although the relationship between LPL and atherosclerosis is not fully understood, there is evidence that suggests that LPL has proatherogenic effects." (PMID 34445740, 2021). "Studies in mice show that macrophages display increased LPL expression in early atherosclerosis and the enhanced LPL expression accelerates foam cell formation." (PMID 34356847, 2021). "While it has previously been demonstrated that severe hypertriglyceridemia promoted atherosclerosis in lipoprotein lipase knockout (LPL−/−) mice, disease progression was very slow, taking more than 1 year to detect atherosclerosis." (PMID 34796210, 2021). "This process is driven by endothelial and macrophage lipoprotein lipase activity, as demonstrated by the observation of less atherosclerosis in mice with inactivated lipoprotein lipase gene." (PMID 32819363, 2020). "This connection between increased LPL activity and inflammation has been thoroughly studied in the context of atherosclerosis." (PMID 32231585, 2020). "The participation of LPL in the pathogenesis of atherosclerosis is two-fold: it mediates both the increased hydrolysis of lipoprotein triglycerides as well as the retention of lipoprotein remnants." (PMID 32231585, 2020). "Strikingly, disease ontology enrichment analysis showed “atherosclerosis and multiple sclerosis,” including LPL as hubgene, involved in lipid metabolism." (PMID 30867424, 2019). "Recent studies have demonstrated the presence of natural autoantibodies in blood of patients with atherosclerosis, such as anti-apolipoprotein A-1 antibodies and anti-lipoprotein lipase antibodies." (PMID 30479572, 2018). "Lipoprotein lipase encoded bythe LPL gene is a key enzyme in lipid metabolism andtransport; it also participates in pathogenesis of atherosclerosis." (PMID 29340220, 2017). "Postprandial lipemia and lipoprotein lipase (LPL) activity play crucial roles in the pathogenesis of accelerated atherosclerosis." (PMID 28814963, 2017). "Enhancing miR-27a/b function protected apoE KO mice from atherosclerosis as a result of obvious reduction of the expression of LPL, lipid uptake, and pro-inflammatory cytokine secretion, but inhibition of miR-27a/b function had the opposite effects." (PMID 27257686, 2016). "In a study conducted on atherosclerosis, IL-6 has been shown to play a pathophysiological role altering lipoprotein lipase (LPL) activity and stimulating lipolysis." (PMID 27413547, 2016). "This conclusion has been substantiated by the observation that macrophage-specific expression of human LPL promotes the development of atherosclerosis in apoE knockout mice and rabbits." (PMID 27257686, 2016).
atherosclerosis (continued). "This study should shed light on the special role that LPL derived from hematopoietic cells in lipoprotein metabolism and atherosclerosis." (PMID 21980507, 2011). "The most critical areas of LPL biology and pathobiology are neural development and neurodegeneration, immunity, atherosclerosis and myocardial injury, and cancer." (PMID 12806020, 2002). "However, depletion of macrophage LPL demonstrated beneficial effects against the development of atherosclerosis." (PMID 39081272, 2024). "Review lipoprotein lipase and its role in diseases like atherosclerosis." (PMID 39044888, 2024). "Consistent with this, there are reports documenting no atherosclerosis in arteries of a >60-year-old women and a 53-year-old man with LpL deficiency." (PMID 39649171, 2024). "Furthermore, estrogen can suppress the expression of pro-inflammatory genes, such as lipoprotein lipase (LPL) and scavenger receptor class B type 1 (SR-B1), both of which are linked to LDL cholesterol accumulation and the onset of atherosclerosis." (PMID 37650466, 2024). "Moreover, LPL has differential effects on several inflammatory pathways that are relevant in atherosclerosis." (PMID 36982268, 2023). "Our investigation into the activity of lipoprotein lipase (LPL)—an enzyme often associated with suppression of atherosclerosis onset—showed that neither natto nor variable vitamin K2 content had a substantial impact on LPL activity." (PMID 38110459, 2023). "Moreover, lipoprotein lipase deficiency in macrophages reduces their VLDL uptake and oxidizes low-density proteins, thereby mitigating the course of atherosclerosis." (PMID 37759485, 2023). "It is believed that LPL plays a significant role in the progression of atherosclerosis." (PMID 36982268, 2023). "In addition, LDL receptor or apoE knockout (KO) mice overexpressing LPL showed protection against atherosclerosis." (PMID 35456470, 2022). "Conversely, LPL, the only protein in our investigation to show a negative relationship with the development of HF, has been associated with less severe atherosclerosis and reduced rates of cardiovascular disease and death." (PMID 35945262, 2022). "In macrophage of LPL knockout mice, the plasma LPL and lipoprotein remained unchanged, cholesterol ester formation and intracellular triglyceride level was reduced and thus interfere with the development of atherosclerosis." (PMID 35241081, 2022). "Thus, previous studies have revealed the importance of ANGPTL4, which is known as a regulator of LPL in cardiometabolic disorders such as atherosclerosis." (PMID 35566578, 2022). "Insufficient LPL activity has been previously suggested as an early factor in atherosclerosis." (PMID 34544430, 2021). "The direct relationship between LPL and atherosclerosis is complex." (PMID 32849290, 2020). "Moreover, LPL expressed in macrophages has detrimental effects on atherosclerosis, which are distinct from its effects on TRL levels." (PMID 32849290, 2020). "Furthermore, exercise has been shown to increase LPL within humans and rats in all age groups, thus suggesting that PA can protect against atherosclerosis through the mediation of the LPL pathway." (PMID 31644560, 2019). "Human LPL transgenic rabbits overexpressing LPL fed a high-cholesterol diet showed hypercholesterolemia but a dramatic reduction of atherosclerotic lesions, suggesting that elevated LPL expression protects against atherosclerosis." (PMID 30959963, 2019).
atherosclerosis (continued). "MiR-134-5p accelerates atherosclerosis by promoting lipid accumulation and inflammatory responses following induction of lipoprotein lipase in macrophages, which explains its higher (3.5-fold) expression in peripheral blood mononuclear cells isolated from patients with unstable angina." (PMID 29762500, 2018). "The effects on changes of LPL and EL mass differed depending on the lipid-lowering therapy, which may impact the prevention of atherosclerosis differently." (PMID 27039080, 2016). "Previous studies have shown that macrophage-derived lipoprotein lipase (LPL) might be a key factor that promotes atherosclerosis by accelerating lipid accumulation and proinflammatory cytokine secretion." (PMID 27257686, 2016). "The present results provide evidence that a novel antiatherogenic role of miR-27 was closely related to reducing lipid accumulation and inflammatory response via downregulation of LPL gene expression, suggesting a potential strategy to the diagnosis and treatment of atherosclerosis." (PMID 27257686, 2016). "In conclusion, the effects on changes of LPL and EL mass were different depending on the lipid-lowering therapy, which may have different impacts on the preventive effects of the therapy on atherosclerosis." (PMID 27039080, 2016). "Therefore, manipulating macrophage LPL to reduce lipid accumulation and inflammatory response has been an important therapeutic goal of atherosclerosis." (PMID 27257686, 2016). "Macrophage expression of LPL promotes foam cell formation and atherosclerosis in vivo." (PMID 26143381, 2015). "LPL in macrophages is known to play a key role in cholesterol homeostasis and pro-atherosclerosis." (PMID 26397958, 2015). "It has been reported that a deficiency of LPL and CETP enzymes are related to the development of atherosclerosis; this deficiency could be related to mutations or variants in their genes, or by altering molecules involved in its metabolism." (PMID 26370976, 2015). "Indeed, macrophage LPL plays an important role in the development of atherosclerosis because of its promoting effects onpro-inflammatory cytokine expression and lipid composition." (PMID 26397958, 2015). "The relationship between LPL and atherosclerosis has been controversial for long time." (PMID 26397958, 2015). "The present data are conclusive in showing that anti-LPL antibodies are not implicated in the pathophysiology of inflammatory atherosclerosis processes of Takayasu's arteritis." (PMID 19606253, 2009). "Given the known impact of plasma cholesterol levels on cardiovascular disease, determining whether V227A reduces LDL or remnant cholesterol levels and whether LPL-mediated plasma cholesterol reduction yields any protection from atherosclerosis would be worth future investigation." (PMID 40245984, 2025). "Additionally, heightened LPL might improve endothelial function, reduce vascular inflammation, and reduce oxidative stress, which is central to the development of atherosclerosis in T2D patients." (PMID 41373652, 2025). "Deficiency of CD36 could impair the clearance of lipoprotein lipase-mediated triglyceride 68, chylomicrons 21 and oxidized LDL 69, indicating the importance of CD36 in controlling the clearance of dietary lipid intake and reducing the risk of atherosclerosis." (PMID 40365299, 2025). "The loss of ANGPTL4 in these tissues increases LPL activity and accelerates the catabolism of triglyceride-rich lipoproteins, reducing circulating triglycerides and low-density lipoprotein–cholesterol (LDL-C), which protects against the progression of atherosclerosis." (PMID 39728292, 2024). "Thus, the effect of macrophage LPL on atherosclerosis could be the result of its lipolytic activity and/or its ability to act as a receptor to assist remnant particle uptake." (PMID 39081272, 2024).
atherosclerosis (continued). "Thus, the contribution of LPL towards the etiology of atherosclerosis is contentious." (PMID 39081272, 2024). "The role of LPL may vary depending on the stage of cancer and subtype, but the time is right to take advantage of the biochemistry of LPL and the knowledge of LPL function in atherosclerosis down a new avenue." (PMID 36652113, 2023). "The authors also found that the LPL HindIII polymorphism increased the risk of coronary artery disease (CAD) and that HindIII polymorphism also showed an association between plasma lipid levels and the risk of atherosclerosis, subsequently leading to coronary artery disease (CAD) and stroke." (PMID 35456470, 2022). "Therefore, inhibition of macrophage LPL by P407 may have contributed to reduced atherosclerosis with P407 injection." (PMID 35681489, 2022). "Increased plasma LPL activity could alter lipid traits, such as decreasing TG and increasing HDL levels, generating a profile associated with protection against atherosclerosis, while the down-regulation of LPL gene expression has been shown to play an opposite role." (PMID 29459423, 2018). "However, it has not been fully understood whether miR-27 affects the expression of LPL and subsequent development of atherosclerosis in apolipoprotein E knockout (apoE KO) mice." (PMID 27257686, 2016). "Several studies have demonstrated that plasma LPL mass concentration could be altered by drug manipulations, such as fibrate, insulin sensitizer, and statins in patients with diabetes, potentially affecting the progression of their atherosclerosis." (PMID 27039080, 2016). "Interestingly, Atherosclerosis Signaling was the second highest IPA pathway, and includes genes previously associated with vascular inflammation, such as IL-37, SERPINA1, S100A8, selectin E/SELE, lipoprotein lipase/LPL, and MMP1/3/9." (PMID 26459294, 2015). "Therefore, it is of particular interest to investigate whether LPL from macrophages plays any role in the LPL deficient severe HTG state, which may provide new insight on the effects of macrophage LPL on lipoprotein metabolism other than atherosclerosis." (PMID 21980507, 2011). "This process is critically mediated by lipoprotein lipase (LPL) and the fatty acid translocase CD36, ultimately leading to reduced plasma lipid levels and conferring protection against atherosclerosis in hyperlipidaemic models." (PMID 41009610, 2025). "Both ANGPTL3 and apoC-III inhibit lipoprotein lipase (LPL), the enzyme responsible for hydrolyzing triglycerides in TRLs, leading to increased circulating TRLs and remnant cholesterol, which promote atherosclerosis." (PMID 41010649, 2025). "In the genomic regions shared by GlycA and atherosclerosis, five nonsynonymous exonic SNPs were mapped to genes FGB, SLC22A1, LPL, SERPINA1, and ANGPTL4, with the following high PPs, H3: 94.5%, H4: 96.8%, H4: 73.7%, H4: 97.2%, and H4: 100%." (PMID 38892172, 2024). "Many studies have shown that CD36, LPL, FADS1, and SCD1 promoted atherosclerosis development by regulating lipid metabolism." (PMID 37324939, 2023). "Antibodies against lipoprotein lipase (LPL), elevated TC, LDL, TAGs, and lower HDL levels are other factors contributing to atherosclerosis and organ damage in SLE patients." (PMID 36297390, 2022).